IL10 (interleukin 10)
Diseases named in the same sentence as IL10 in open-access papers (continued):
Sharing a sentence is not in itself a finding about the gene and the disease.
acute pancreatitis (continued). "Interleukin (IL)-10, a potent anti-inflammatory cytokine, is released during acute pancreatitis and is known to limit inflammatory responses by downregulating the release of proinflammatory mediators." (PMID 23285260, 2012). "It is well known that interleukin-10 (IL-10) limits the severity of acute pancreatitis in mice, therefore we detected the IL-10 cytokine level in the peripheral blood of mice during the development of cerulein-induced acute pancreatitis by ELISA." (PMID 22956998, 2012). "In this way, the mechanism of IL-10 as the direct target of Shh signaling pathway to confront acute pancreatitis in mice was elucidated." (PMID 22956998, 2012). "Molecular biological studies showed that autocrine Shh signaling activated the key transcriptional factor Gli1 so that the target gene IL-10 was upregulated, leading to the protective and anti-inflammatory functions in the mouse model of acute pancreatitis." (PMID 22956998, 2012). "Interleukin (IL)-10, a potent anti-inflammatory cytokine, was reported to be released during the course of experimental acute pancreatitis and was shown to limit the severity of this disease by downregulating the release of proinflammatory mediators." (PMID 23285260, 2012). "Mechanistic insight into Shh signaling activation in acute pancreatitis indicates that inflammatory stimulation activates Shh expression and secretion, and subsequently upregulates the expression and secretion of interleukin-10 (IL-10)." (PMID 22956998, 2012). "Molecular biological studies show that autocrine Shh signaling activates the key transcriptional factor Gli1 so that the target gene IL-10 is upregulated, leading to the protective and anti-inflammatory functions in the mouse model of acute pancreatitis." (PMID 22956998, 2012). "Especially in cases of severe acute pancreatitis increased serum levels of IL-10 could be observed, which indicates a shift from proinflammation to immunosuppression." (PMID 40560328, 2025). "Also, it has been stated that proinflammatory cytokines (TNFα, IL-1β, and IL-6) were significantly reduced, whereas antiinflammatory cytokines (IL-10 and IL-4) were increased in animals with acute pancreatitis pretreated with melatonin." (PMID 38333760, 2024). "Additionally, pirfenidone has been shown to augment the IL-10-driven anti-inflammatory pathway in macrophages, contributing to its effectiveness in treating acute pancreatitis." (PMID 38881734, 2024). "TNF- α and IL-10 are cytokines that have been well studied in acute pancreatitis." (PMID 35041718, 2022). "One animal study done in experimental acute pancreatitis rat model showed that rats intravenously treated with fish oil (mainly omega-3 fatty acids) had significant higher level of interleukin (IL)-10 (an anti-inflammatory cytokine) together with fewer episodes of respiratory dysfunction." (PMID 36299997, 2022). "IL-10 is thought to play a protective role in acute pancreatitis." (PMID 33803665, 2021). "Furthermore, an experimental study showed that IL-10 production was induced in mice upon infection with CVB and appeared to facilitate the development of chronic pancreatitis, as IL-10 knockout animals resolved the acute pancreatitis." (PMID 31401790, 2019). "The pretreatment of IL-10 could decrease the severity of cerulein-induced acute pancreatitis in mice by inhibiting cellular necrosis." (PMID 27314021, 2016). "A possible explanation is that IL-10 could be secreted from other cell types apart from BM cells during the episodes of acute pancreatitis induced by cerulein, and this is sufficient to maintain basic IL-10 levels during the acute inflammatory response." (PMID 27314021, 2016). "We performed in vitro experiments to elicit whether the increased IL-10 in mice blood serum was from acinar cells, because during the acute pancreatitis cells from immunity system as well as other tissues are the main source of IL-10 secretion." (PMID 22956998, 2012).
acute pancreatitis (continued). "Previous studies have shown a role of IL-10 in reducing the severity of acute pancreatitis and ALI." (PMID 23110041, 2012). "Based on these findings and theories, we hypothesize that the anti-inflammation effect of Shh in acute pancreatitis in mice is achieved, at least partly, by upregulating IL-10 gene expression." (PMID 22956998, 2012). "Interestingly, serum levels ofanti-inflammatory molecules such as IL-10, IL-1β receptor antagonist, andsoluble IL-2 receptor (sIL-2r) were also found significantly higher in patientswith acute pancreatitis." (PMID 18670651, 2008). "Moreover, the expression of IL-10 may suppress acute pancreatitis, and notably, Sawada found that IL-10 and its downstream STAT3 pathway regulate the proliferation of cells infected with HTLV-1." (PMID 33556114, 2021). "Published reports show that IL-10 attenuates the inflammatory response and decreases TNF-α secretion in acute pancreatitis." (PMID 29497350, 2018). "Although we measured only IL-6 and TNF, other inflammatory mediators known to play a critical role in acute pancreatitis and MODS include TNFa, IL-1b, IL-6, IL-8, platelet-activating factor, and IL-10." (PMID 20015376, 2009). "Persistent activation of PSCs by cytokines during acute pancreatitis such as TNF-α, IL-1, IL-6, and IL-10, may be a factor involved in the progression from acute pancreatitis to chronic pancreatic injury and fibrosis." (PMID 39759120, 2025). "In fact, there is some evidence that DENV infection ultimately elicits production of cytokines such as tumor necrosis factor alpha, transforming growth factor beta, and interleukin 10, otherwise observed in studies on non-DENV-associated acute pancreatitis." (PMID 41441569, 2025). "Until now, IL-10 has not been investigated in relation to necroptosis, but it has been shown that IL-10 can prevent necrosis in murine experimental acute pancreatitis implying a potential protective role of IL-10 in necroptosis." (PMID 38448513, 2024). "Studies have shown that IL-10 can limit plasma TGF-β1 levels and activated PSC numbers during recurrent acute pancreatitis episodes, effectively restraining the production of type I and type III collagen proteins and mitigating potential fibrosis and glandular atrophy processes associated with CP." (PMID 38255213, 2024). "Furthermore, IL-10 attenuated the increase in BBB permeability and the downregulation of claudin-5 in a rat model of severe acute pancreatitis." (PMID 36882782, 2023). "The IL-10-induced decrease in TNF-α secretion might be helpful in stabilizing the BBB, as TNF-α has been reported to increase BBB permeability in acute pancreatitis." (PMID 29497350, 2018). "However, in severe acute pancreatitis, there is extensive acinar cell injury, which leads to neutrophil, monocyte, and lymphocyte activation, and this results in the secretion of plenty of inflammatory mediators such as TNF-α, IL-6, and IL-10." (PMID 35296066, 2022). "DCQD treatment could increase the expression of anti-inflammatory cytokines (IL-4 and IL-10) and inhibit the expression of proinflammatory cytokines (TNF-α and IL-6) to ameliorate the histopathological damage of acute pancreatitis, in which higher dose DCQD seems to have the better effect." (PMID 26199633, 2015). "But whether IL-10 is a target gene of Shh signaling in cerulein-induced acute pancreatitis has never reported." (PMID 22956998, 2012). "Platelet-activating factor antagonists such as lexipafant, antioxidants, corticosteroids, nitroglycerin, anti-interleukin-10 (anti-IL-10) antibodies, and anti-tumor necrosis factor-alpha (anti-TNF-α) antibodies have been shown to be of no value in the treatment of acute pancreatitis." (PMID 26918139, 2015).
acute kidney injury (55 papers, 2012 to 2026). Sudden and sustained deterioration of the kidney function characterized by decreased glomerular filtration rate, increased serum creatinine or oliguria. "IL-10 stimulates mesangial cell proliferation and increases the synthesis and secretion of various growth factors, cytokines, and chemokines, causing renal failure." (PMID 36552226, 2022). "We proved that IL-10 deficiency aggravates renal failure in obese condition through lipid accumulation, renal histopathology, inflammatory cells infiltration, pro-inflammatory cytokines/chemokines secretion, fibrosis and functional analysis." (PMID 33547567, 2021). "This study suggests that IL-10 ought to be regarded as a unique biomarker for predicting or monitoring renal failure in MM patients, in addition to being a possible candidate for targeted therapy as previously indicated." (PMID 40647640, 2025). "Ori has been shown to ameliorate acute kidney injury by inhibiting macrophages-mediated inflammation, and suppressing the expression of cytokines IL-2, IL-4, IL-6, IL-10, and TNF-α, suggesting that Ori had a potent anti-inflammatory response activity." (PMID 37375489, 2023). "Under normal circumstances, the level of serum IL-10 begins to decrease after 24-28 hours and gradually becomes normal in mouse acute kidney injury model." (PMID 33204326, 2020). "In this study, we examined the cellular sources of IL-10 and their functional relevance during cisplatin-induced acute kidney injury." (PMID 32898157, 2020). "We reported that cisplatin enhances renal IL-10 signaling and that endogenous production of IL-10 reduced cisplatin-induced acute kidney injury." (PMID 32898157, 2020). "In the present study, we investigated the association of 12 polymorphisms in six inflammatory-response genes (TNF, IL6, IL10, IL18, NFKB1 and NFKBIA) with risk of acute kidney injury (AKI) in children." (PMID 30429237, 2018). "It was of interest to note that when considering the patients with renal failure and liver failure, the IL-17 and IL-10 cytokine levels were lower compared to the healthy controls." (PMID 30123395, 2018). "Despite having anti-inflammatory properties, increased serum level of IL-10 is a predictor of increased mortality in patients with acute kidney injury." (PMID 29535870, 2018). "IL-10, mainly produced by renal DCs, attenuates cisplatin nephrotoxicity and protects from cisplatin-mediated acute kidney injury." (PMID 28828008, 2017). "Moreover, studies indicating that elevated serum IL-10 levels correlate with renal failure have captured our interest." (PMID 40647640, 2025). "Immunosuppression in sepsis may be closely linked to the development of acute kidney injury (AKI), and sCD25 or IL-10 may be useful as novel biomarkers for the development of septic AKI." (PMID 41225969, 2025). "It is therefore proposed that the use of epigenomic editors which activate antifibrotic genes, including RASAL1, KL, and IL-10, may represent a promising approach for the treatment of acute kidney injury and fibrosis." (PMID 40650152, 2025). "In addition, the analysis of this cytokine in patients suffering from acute kidney failure showed an increase in serum IL-10 levels, which correlated with a poor prognosis." (PMID 37425258, 2023). "In addition, the microalbuminuria and renal failure groups had lower IL-10 concentrations than the normal group (P < 0.05), and the microalbuminuria group also had a lower IL-10 concentration than the macroalbuminuria group (P < 0.05)." (PMID 33859989, 2021). "Both endogenous and exogenous IL-10 are protective in cisplatin-induced acute kidney injury." (PMID 32898157, 2020). "IL-10 is mainly eliminated by the kidneys, and thus, its plasma half-life may be increased in renal failure." (PMID 31861622, 2019). "The major producers of IL-10 in the kidneys are the mesangial cells, whose abnormal proliferation structurally alters the glomeruli and interstitial tubules and may result in renal failure." (PMID 31227794, 2019).
acute kidney injury (continued). "Indeed, high plasma IL-10 levels correlated with the presence of respiratory and renal failures in our cohort." (PMID 28432351, 2017). "The mRNA abundance of cytokines (IL-1α, IL-1β, IL-8, IL-10, TNF-α, TGF-β) and enzymes (5-LO, iNOS) was measured prospectively in blood leukocytes from 34 dogs with severe leptospirosis and acute kidney injury, including 22 dogs with leptospirosis-associated pulmonary hemorrhages." (PMID 26824356, 2016). "In addition, anti-inflammatory effects bvPLA2 was also mediated by IL-10 secretion and Treg activation in cisplatin-induced acute kidney injury model." (PMID 27669297, 2016). "Interleukin-10 (IL-10) encapsulated in EVs showed increased stability and precise targeting in the treatment of acute kidney injury (AKI)." (PMID 40428144, 2025). "Interleukin-10 (IL-10), a kind of anti-inflammation cytokine, has a key role in the development of acute kidney injury (AKI)." (PMID 34090357, 2021). "In other pathological conditions, such as in acute kidney injury, GPNMB functions as a negative regulator of inflammation by promoting IL-10 and TGF-β secretion." (PMID 29123519, 2017). "Increased levels of for example serum IL-6, IL-10, and HMGB-1 were reported in pigs and mice in more severe models of local inflammation such as multiple trauma and acute kidney injury." (PMID 27250718, 2016). "Though in acute kidney injury the TNF-α gene, transforming growth factor β1 gene (TGF-β1), and interleukin 10 gene (IL-10) have more important effects on regulation of inflammatory response." (PMID 24282796, 2013). "Similarly, patients who developed acute kidney injury (AKI) requiring CRRT had elevated baseline concentrations of CXCL10 (Δ = 3236, 95% CI 1014–5459), IL-10 (Δ = 48.6, 95% CI 34–63), IL-8 (Δ = 39.9, 95% CI 17.7–62.1) and IL-6 (Δ = 1441, 95% CI 125–2697)." (PMID 40869413, 2025). "Moreover, CIS reduced serum testosterone levels and diminished testicular IL-10, as well as CIS-induced renal failure, as indicated by hypokalemia, and increased levels of creatinine, urea, sodium, IL-18, and KIM-1." (PMID 39459023, 2024). "This renal failure was determined by higher levels of TNF-α, CRP, IL-6, and IL-10." (PMID 36851766, 2023). "Moreover, PLA2, one of the main components of bee venom, was shown to control the expression of interleukin (IL)-10 and Tregs by binding to CD206, protect against cisplatin-induced acute kidney injury (AKI), and prevent inflammatory responses." (PMID 32899913, 2020). "However, the source of IL-10 which accounts for this renal protection during acute kidney injury is not known." (PMID 32898157, 2020). "Similarly, in acute kidney injury, GILZ was markedly suppressed by inflammation, and treatment with exogenous GILZ resulted in decreased IL-17, increased regulatory T cells (Treg) and IL-10, and prevention of cell death, demonstrating the renoprotective role of T cell GILZ." (PMID 33889157, 2021).
pulmonary TB (55 papers, 2009 to 2025). "High level of IL-10, at the end of treatment in pulmonary TB patients, was also associated with TB recurrence, indicating that IL-10 plays an essential role in TB pathogenesis and disease progression." (PMID 31921181, 2019). "Thus, both Th1 and aTreg cells expressing IL-10 appear to be associated with the degree of pathology in active pulmonary TB." (PMID 26417443, 2015). "In active pulmonary tuberculosis IFNγ and IL-10 are produced by Th1 T cells supporting the fact that IL-10 production is not confined to Tregs and Th2 cells." (PMID 35867720, 2022). "Regarding extrapulmonary TB, lower levels of IFN-γ, IL-2, IL-10 and IL-17 were observed in patients in this group compared with pulmonary TB." (PMID 36296351, 2022). "Jamil and colleagues established that IFNγ/IL-10 correlated with disease severity in both pulmonary TB and extrapulmonary TB." (PMID 35025927, 2022). "In pulmonary TB, the high concentrations of IL-6/IL-10 and STAT-3 led to the impaired function of T cells." (PMID 36439164, 2022). "Clostridium members are short-chain fatty acid (SCFA) producers inducing anti-inflammatory production (IL-10), and SCFAs metabolites are acknowledged to modulate immune and proinflammatory responses to pulmonary TB." (PMID 33036349, 2020). "Filarial infection is associated with elevated regulatory cytokines (IL-10 and TGF β) in pulmonary TB." (PMID 32373129, 2020). "IL-10 together with IP-10 and IL-4 differentiated pulmonary tuberculosis from latent cases with a sensitivity and specificity of 77.1% and 88.1%, respectively." (PMID 32962082, 2020). "IL10 combined with CXCL-9 distinguished pulmonary tuberculosis patients from extrapulmonary cases with a sensitivity, specificity, and accuracy of 85.7%, 73.9%, and 81.0%, respectively." (PMID 32962082, 2020). "To date, PPE59 it is known to induce cell-mediated response by IFN-γ and interleukin-10 in pulmonary TB and, as a result of our study, immunodominance of PF IgA but non-IgG in PLTB patient." (PMID 31623558, 2019). "Some studies have revealed the changes of interleukin 10 and 13 in relation to pathology of pulmonary tuberculosis." (PMID 31363402, 2019). "IL-10, which is a suppressor T cell or T-regulatory cytokine, is known to play a critical role during chronic and latent stages of pulmonary TB." (PMID 30583589, 2018). "Recombinant human IL-10 was used to investigate the regulation of IL-17 expression after sputum smear conversion in AFB-positive pulmonary TB patients." (PMID 27311307, 2016). "IL-10 which is a T regulatory cytokine plays a central role during chronic and latent stage of pulmonary TB." (PMID 26359865, 2015). "Neutralization of endogenous IL-10 in peripheral blood mononuclear cells (PBMC) of pulmonary TB patients enhanced T-cell proliferation and IFNγ production." (PMID 24350246, 2013). "We particularly believe that the increased production of IL-10 after clinical cure of pulmonary tuberculosis occurs due to memory T cells." (PMID 23824716, 2013). "Pulmonary TB patients displaying the highest concentrations of HO-1 in plasma exhibited significantly elevated plasma levels of interleukin (IL)-10, interferon (IFN)-γ and IL-17 and diminished levels of tumor necrosis factor (TNF)-α." (PMID 23671613, 2013). "Neutralization of endogenous IL-10 in PBMCs from pulmonary TB patients resulted in increased T-cell proliferation and IFN-γ production, with enhanced proliferative responses to PPD in patients with anergic TB." (PMID 23320781, 2013). "Pulmonary TB is characterized by an IL-10 dependent antigen-specific suppression of Type 1, Type 2 and Type 17 cytokines, reflecting an important association of these cytokines in the pathogenesis of active TB." (PMID 23544075, 2013). "IL-10 levels in peripheral blood cells and serum of active pulmonary TB patients were shown to be raised." (PMID 23320781, 2013).